CLDN1 (claudin 1)
Diseases named in the same sentence as CLDN1 in open-access papers (continued):
Sharing a sentence is not in itself a finding about the gene and the disease.
infection (continued). "Consequently, a mechanistic description of how the susceptibility of cells to infection depends on CLDN1 expression remains difficult to construct." (PMID 22545157, 2012). "However, the H316N mutation in HCV-JFH1-tau Lot B1 was unnecessary for CLDN1-independent infection." (PMID 36424447, 2022). "Functional studies revealed that claudin-1 overexpression enhanced cellular susceptibility to TGEV, PEDV, and PDCoV, whereas its knockout significantly attenuated infection." (PMID 41511114, 2026). "As many studies reported, the infection of E. coli can reduce the mRNA expressions of ZO-1, Mucin2, and Claudin-1 in broilers through the activation of the NF-κB signaling pathway." (PMID 41514770, 2025). "In this study, we observed that infection with ETEC significantly reduced the mRNA levels of Claudin-1 and ZO-1 in the jejunal mucosa of weaned piglets." (PMID 40087676, 2025). "In cells infected with wild-type SC1401, the levels of claudin-1 and occludin increased through 12 h and 36 h of infection, respectively, before decreasing to time 0 levels or lower." (PMID 38674155, 2024). "In cells infected with ΔEspP2::Kan, levels of occludin and claudin-1 decreased significantly throughout the 48 h infection." (PMID 38674155, 2024). "First, viruses directly utilize CLDNs as bind/entry factors to initiate infection; e.g., CLDN1 acts as a co-receptor for hepatitis C virus (HCV)." (PMID 39459923, 2024). "The relative mRNA expression of ZO-1, Claudin-1, and Occludin in the ileum and colon was significantly decreased after S. Typhimurium infection, especially 72 hours post-infection." (PMID 39435479, 2024). "Infection of porcine choroid plexus epithelial cells S. suis resulted in Claudin-1 and ZO-1 rearrangement, disorganization, and barrier disruption." (PMID 38874395, 2024). "The IHC results showed that compared with normal mouse duodenal villi, the immune-positive signals of ZO-1, Occludin, and Claudin-1 in the duodenal mucosa were weakened to varying degrees after CPA infection." (PMID 39195835, 2024). "On the day 1 of infection, the mRNA transcript levels of tight junction proteins (Claudin-1 and Occludin) and mucin (MUC-2) were significantly reduced in the jejunum and ileum of chicks in the SP group compared to the NC group." (PMID 38863452, 2024). "In HeLa cells, the mRNA of CLDN1 was especially sensitive to the HAZV infection, with approximately 20-fold increase." (PMID 37287449, 2023). "LDN1/CLDN6 double-knockout Huh-7.5 cells support infection by a mutant HCV only when CLDN1, CLDN6, or CLDN9 is expressed." (PMID 38203503, 2023). "Virus production in HeLa/CLDN1 was approximately 3- and 10-fold lower than that in the control cell line (HeLa/ctrl) at 24 and 48 h post-infection (hpi), respectively." (PMID 37287449, 2023). "Previous studies have reported that TNF-α increases the expression of CLDN1 in human epithelial cells, and the possibility of increased expression following infection was also mentioned due to the anti-apoptotic effect of CLDN1." (PMID 37799512, 2023). "This correlated well with intermediate epithelial damage, as depicted in histological analysis and with the change in the CLDN1 gene expression with the infection." (PMID 37680750, 2023). "The G. parasuis serotype 5 SQ strain (HPS5-SQ) infection decreased the integrity of piglets’ lung Occludin and Claudin-1." (PMID 36228044, 2022). "As expected, infection with ETEC significantly (P < 0.05) reduced the relative expression of claudin-1, occludin, and zona occludens-1 mRNAs." (PMID 35736372, 2022). "Whereas HCV-JFH1-tau infection depends only on CLDN1, HCV-JFH1-tau/M706L infection exhibited the expanded receptor usage options: CLDN1, CLDN6, and CLDN9 proteins." (PMID 36424447, 2022). "Here we show that STEC Claudin-1 covering mitochondria is enveloped and degraded by autophagy in the infection of HPS5-SQ." (PMID 36228044, 2022).
infection (continued). "IFA and Western blot analysis in the porcine tracheal epithelial cells infection model showed a downregulated Claudin-1 level in STEC cytoplasm and cell membrane." (PMID 36228044, 2022). "Indirect immunofluorescence staining (IFA) and Western blot were used to detect Claudin-1 in cells to explore the effect of HPS5-SQ infection on STEC Claudin-1." (PMID 36228044, 2022). "Since the transepithelial transport of ions is mediated by pores formed by integral membrane proteins termed claudins, we next investigated the expression and localization of claudin-1 during RV-C15 infection in HAE." (PMID 34995322, 2022). "It has also been shown that claudin-1 and claudin-3 relocate from the membrane into the cell cytoplasm following infection with certain pathogens." (PMID 34867313, 2021). "Claudin-1 mRNA expression in the ileum was statistically significantly upregulated by the infection with S. Typhimurium in the LT2 and BB12 + LT2 groups." (PMID 33670419, 2021). "The mRNA levels of claudin-1, claudin-3, claudin-7, claudin-11, occludin and ZO-1 were all downregulated in the case of infection with A. hydrophila (P < 0.05)." (PMID 34220849, 2021). "In contrast, SCBN incubation with PA (0.3 mM) prior to infection resulted in a significant reduction of ZO-1, claudin-1 and claudin-4 expression compared to control cells exposed to PA (0.3 mM) alone (n = 4)." (PMID 34552170, 2021). "Whilst ablation of CD81, Claudin-1 and Occludin abolished infection for all four tested strains, a proportion of all strains was still able to infect SR-B1 knock-out cells." (PMID 33147126, 2021). "After the infection, reduced expression and disordered distribution of ZO-1 and Cldn-1 were detected from IS to the cauda suggesting that the integrity of the BEB is severely disrupted in entire epididymis by ZIKV." (PMID 33667230, 2021). "We noticed that change of Claudin-1 in localization from membrane to cytosol hampered the integrity of tight junctions in the PAO1 group, suggesting that PAO1 infection caused more severe lung barrier damages than ΔoprC strain." (PMID 32849593, 2020). "Investigations of tight junction proteins in the same experimental setting using immunostaining revealed infection-induced alterations in claudin-1, claudin-2 and in occludin expressions." (PMID 30837987, 2019). "Claudin-1 was significantly downregulated early (0-8h) and mid-infection (9-18h) in the OE129-WT cells, but eventually recovered to the levels of the mock-infected controls by 20hrs post-infection." (PMID 30625140, 2019). "After infection the typical chicken wire pattern of claudin-1 and claudin-2 disappeared and the proteins formed conglomerates." (PMID 30837987, 2019). "E. faecium addition markedly increased claudin-1 mRNA expression 3 and 7 days post-infection (P < 0.05)." (PMID 29948799, 2019). "Claudin-1 protein expression levels remained mostly stable at mid-infection (12h) in the OE-129WT cells while only slightly increasing very late during infection; however, its distribution remained mostly stable at the cell-cell junctions throughout infection." (PMID 30625140, 2019). "Feeding chickens with E. faecium upregulated the expression of claudin-1 3 and 7 days post-infection." (PMID 29948799, 2019). "The mRNA expression of claudin-1 significantly increased by E. faecium (P < 0.05) 3 and 7 days post-infection, and Mucin2 was markedly enhanced (P < 0.05) 3 days post-infection." (PMID 29948799, 2019). "As shown, claudin-2 and claudin-3 proteins were expressed in the OE-129WT cells, and their expression levels either remained steady or were increased late during infection, while claudin-1 protein expression appeared to be diminished after the 20hr time-point." (PMID 30625140, 2019). "The transcription of claudin-1 increased after the infection of the germ-free piglets with the wild-type Salmonella Typhimurium and the ΔrfaL mutant." (PMID 31540295, 2019).
infection (continued). "Cldn1-specific neutralizing antibodies only partially inhibited infection of Huh7.5 cells by HCV strains with broad claudin tropisms, suggesting a possible escape from Cldn1-specific targeting molecules through Cldn6 or Cldn9 in cell culture." (PMID 31561440, 2019). "It is known that GS infection delocalizes the tight junctions claudin-1 and occludin in polarized Caco-2 cells but herein, we further show effects on amot (scaffolding protein) and mpp5 (PDZ protein that binds tight junction proteins, also known as Pals1)." (PMID 30062089, 2018). "CLDN1 is able to render 293T cells permissive for HCV entry and antibodies directed against CLDN1 inhibit in vitro and in vivo infection." (PMID 26561856, 2015). "Significantly increased expression of the junction proteins claudin-1 and E-cadherin as well as the keratins K10 and K16 was evident at 8 hours post-infection." (PMID 26601609, 2015). "Prior to infection, cells were screened for the presence of microvilli by electron microscopy and stained for junction proteins (zonula occludens-1, claudin-1, and β-catenin)." (PMID 23755105, 2014). "In caco-2 cells, the levels of TJ membrane proteins claudin-1 and occludin and also the adherens junction proteins β-catenin and E-cadherin was drastically reduced at day 2 post-infection whereas the effect was marginal on α-catenin." (PMID 23894488, 2013). "In agreement with the previous findings showing downregulated expression of OCLN and CLDN-1 in Huh7 cells after infection with JFH-1 HCVcc, the level of OCLN and CD81 expression significantly decreased in Jurkat T cells infected with native HCV." (PMID 23626783, 2013). "For example, at 24 h post-infection, claudin-1 mRNA levels were >1.8 fold higher than in mock-treated cells and at 72 h post-infection, they were 3.9 times higher (p = 0.039)." (PMID 22655077, 2012). "Recent studies have made disparate observations of the modulation of the expression of CLDN1 on cells following infection by HCV." (PMID 22545157, 2012). "With this assumption and without requiring explicit modulation of CLDN1 expression by HCV, our model fit the observed distribution of CLDN1 expression at day 5 post-infection, giving us confidence in our model." (PMID 22545157, 2012). "This drop in the mean CLDN1 expression also explains the observed resistance of the cells in culture at day 5 post-infection to HCV pseudo-particle (HCVpp) entry." (PMID 22545157, 2012). "We found that the mean CLDN1 expression was greater on infected cells than uninfected cells at any time post-infection." (PMID 22545157, 2012). "In contrast, for subpopulations with low CLDN1 expression, proliferation dominated infection so that continued to grow and the total subpopulation continuously increased." (PMID 22545157, 2012). "Our data indicate that all viruses compared by us need CLDN1 for cell entry, since receptor-specific antibodies inhibited infection by each virus in a dose-dependent fashion." (PMID 20617177, 2010). "Claudin-1 is expressed in all hepatoma cell lines permissive to HCVcc and HCVpp infection, except for Bel7402, as well as primary hepatocytes." (PMID 19643019, 2009). "Claudin-1 expressing 293T cells were also permissive to HCVcc infection, although efficiency of infection was 1000 folds less than Huh7 cells." (PMID 19643019, 2009). "Down regulation of claudin-1 via siRNA resulted in a decrease in infection levels of HCVpp and HCVcc." (PMID 19643019, 2009). "Infection with E. coli K99 markedly decreased ZO-1, occludin, and Claudin-1 expression." (PMID 39769422, 2024). "Consistently, we also found that ST infection dramatically reduced the expression of Occludin and Claudin-1, whereas LP postbiotics as well as the live probiotic could prevent the decrease, indicating their ability to enhance mucosal barrier." (PMID 37893938, 2023). "CLDN1-transduced HEK293T cells were susceptible to HCVpp infection, whereas no signal was detected for GBVBpp." (PMID 37310242, 2023).
infection (continued). "Consistently, GBVBpp infection was observed when EL2 of CLDN1 was introduced into CLDN9 (ChimC)." (PMID 37310242, 2023). "The expression of claudin-1 in the ileum reduced significantly after infection with T.gondii." (PMID 37719029, 2023). "Similarly, knockout of CLDN1 in Huh-7.5 cells promoted their resistance to infection with the HCV genotype 2a Jc1." (PMID 38203503, 2023). "However, pretreatment with L. plantarum before infection improves the barrier conditions, maintaining levels of Claudin-1 and Zonulin (up to 24 h of infection), similar to the uninfected control." (PMID 38132754, 2023). "The expression of ZO-1, OCLN, and CLDN-1 was also determined in nasal microvessels to validate whether PEDV infection disrupts the integrity of nasal microvessels." (PMID 35435723, 2022). "Moreover, infection of Huh7.5.1-8 cells with wild-type HCV-JFH1-based HCVpp was strongly inhibited by anti-CLDN1 mAb, whereas infection of Huh7.5.1-8 cells with HCV-JFH1-based HCVpp having M706L was not." (PMID 36424447, 2022). "At the same time, STEC Claudin-1 decreased in the infection of HPS5-SQ for 12 h." (PMID 36228044, 2022). "Cell damage may result in the release of intracellular LDH and Claudin-1 after 24 h infection with HPS5-SQ." (PMID 36228044, 2022). "However, claudin-2 protein expression was decreased and fully restored to control levels by resveratrol, while claudin-1 expression was increased after infection and was unchanged by resveratrol." (PMID 33935732, 2021). "Consequently, butyrate upregulates Cldn1 (encoding Claudin-1) and Ocln (encoding occludin) in a HIF-1-dependent manner, thereby conferring resistance to barrier disruption and bacterial translocation upon infection with Clostridium difficile." (PMID 33968085, 2021). "In present study, we observed that the mRNA expression of occludin, ZO-1, and claudin-1 and protein expression of occludin was significantly lower in AA-ST group than that in AA group, which indicated that AA was helpful for infection/invasion of S. Typhimurium to TJ proteins in ileum." (PMID 34945541, 2021). "The mRNA levels of CLDN1 at 7 d PI were significantly affected by infection (P = 0.0118)." (PMID 33652244, 2021). "Additionally, the results of the confocal imaging were supported this view, the distribution of claudin-1 in LPS infection was observed to have the stronger discontinuous distribution and fainter staining than ZO-1 and occludin." (PMID 31949265, 2020). "Infection of S. aureus significantly degraded occludin, claudin-1, ZO-1 and JAM-1, and preincubation with L. fermentum NCU3087 or L. fermentum NCU3088 significantly attenuated degradation of these tight junction proteins, but still had a significant difference with the control group." (PMID 33042071, 2020). "Similarly, immunostaining of the Caco-2 cells confirmed more severe membrane mislocalization of Claudin-1, Occludin, and E-cadherin after infection with the strains carrying spvB at 3 h p.i.." (PMID 33392110, 2020). "Claudin-1 was upregulated by infection with S. Typhimurium in the ileum." (PMID 33333934, 2020). "In addition, claudin-1 in the TJs opened by PSaV infection facilitates PSaV entry and infection as an entry factor." (PMID 30463963, 2019). "C83091 infection stimulated pBD-2, claudin-1 and claudin-2 mRNA expression in IPEC-J2 cells." (PMID 31221216, 2019). "Nevertheless, during HCV-infection, miR-155 CLDN1 interaction is still elusive." (PMID 29616082, 2018). "While CD81 alone is not sufficient for HCV entry, a recently published mouse model expressing known human entry receptors demonstrated that CD81 had to be co-expressed with occludin, scavenger receptor type B class I, and claudin 1 for optimal infection of murine hepatocytes." (PMID 29121670, 2017). "To test whether overexpression of either CLDN1 or OCLN could render Raji cells more susceptible to infection by hepatotropic JFH-1, we overexpressed CLDN1 or OCLN in Raji cells." (PMID 28067225, 2017).
infection (continued). "Moreover, it was reported that the intestinal tight junction proteins claudin-1, claudin-4 and occludin mRNA expression in the jejunum at 14 days post infection (dpi) were significantly decreased by a S. Typhimurium challenge in broilers." (PMID 28208612, 2017). "Likewise, in HEK293 cells, CLDN1 expression enhanced the efficiency of HCVpp infection to a level similar to that in Huh-7.5.1 cells, but there were not many infected cells after HCVcc infection, although HCV-positive cells were observed." (PMID 27302754, 2016). "In addition to the four essential factors for HCV entry, CD81, SR-BI, claudin-1 and occludin, several additional factors facilitate infection." (PMID 25701818, 2015). "To determine whether HCVpp expressing patient-derived envelope glycoproteins required claudin-1 to initiate infection we assessed their ability to infect the claudin-null cell line, 293T, and CC-LP-1 cells following claudin-1 overexpression." (PMID 25701818, 2015). "However, the same viruses infected parental CC-LP-1 cells, however, their infection levels were increased following claudin-1 expression in this cellular background." (PMID 25701818, 2015). "Infection of human cell lines and primary hepatocytes can be blocked by specific antibodies directed against CLDN1 and kinetics of inhibition with such antibodies showed that CLDN1 acts cooperatively with CD81 and SR-BI in HCV entry." (PMID 24509809, 2014). "For subpopulations with high CLDN1 expression, infection dominated proliferation." (PMID 22545157, 2012). "Indeed, in the experimental distribution of CLDN1 expression at day 5 post infection, a tiny peak appears in the high CLDN1 region possibly because here other entry receptors limit entry." (PMID 22545157, 2012). "Furthermore, antibodies specific for claudin-1 ECL1 inhibit HCV infection by reducing claudin-1 association with CD81, highlighting the therapeutic value of targeting the receptor complex to limit infection." (PMID 22897233, 2012). "CLDN1 also appears to be necessary for cell-cell transmission of infection." (PMID 22545157, 2012). "typhimurium-induced inflammation, reduced bacterial adherence, upregulated claudin-1, preserved gut homeostasis, ameliorated tissue lesions, and increased the abundance of Lactobacillus in the cecum, demonstrating promising potential for poultry infection control." (PMID 42117980, 2026). "An in vitro study showed that infection with Porphyrormonas (P.)gingivalis increased the expression of the IL-31 receptor (IL-31R) in human gingival epithelial cells and that IL-31 in those cells downregulates the P. gingivalis-induced overexpression of claudin-1." (PMID 37958576, 2023). "Therefore, although further investigations are needed, we suppose that the V392A mutation is involved in but not enough for the CLDN1-independent infection phenotype of HCV-JFH1-tau Lot B1, and additional mutations are necessary." (PMID 36424447, 2022). "The scope of claudin-1 induction gradually decreased in piglets infected with Δrfa mutants, with the decreasing completeness of their lipopolysaccharide chains in the direction of ΔrfaL > ΔrfaG > ΔrfaC, corroborating with decreasing severity of the infection as evaluated by clinical signs." (PMID 31540295, 2019). "Our study also indicates the inner foreskin of males at risk of infection has TJ alterations such as the absence of membrane-bound claudin 4, extended membrane localization of claudin 1, and a more intense occludin staining pattern, suggestive of permeability differences." (PMID 25268493, 2014). "In addition, evidence was reported that sub-optimal usage of mouse CLDN1 and SR-BI may also limit efficient infection of mouse cells." (PMID 20617177, 2010). "Infection of HOKs with P. gingivalis, the key periodontal pathogen, significantly downregulated OCLN, CLDN1, and CDH1." (PMID 41358003, 2025).